GRK6 (G protein-coupled receptor kinase 6)
Diseases named in the same sentence as GRK6 in open-access papers (continued):
Sharing a sentence is not in itself a finding about the gene and the disease.
chronic kidney disease (1 paper, 2021). Impairment of the renal function secondary to chronic kidney damage persisting for three or more months. "The F12/GRK6 locus has additionally been associated with chronic kidney disease." (PMID 33961016, 2021).
colitis (1 paper, 2022). Inflammation of the colon. "Additionally, acute dextran sodium sulphate induced colitis showed a higher rate of transition to chronic colitis in GRK6-deficient mice." (PMID 36555521, 2022). "Firstly, signs of increased post-inflammatory visceral hyperalgesia in response to intracolonic treatment with capsaicin could be detected in female GRK6-knockout mice in comparison to wild-type mice after recovery from dextran sodium sulphate triggered colitis." (PMID 36555521, 2022).
epilepsy (1 paper, 2017). A brain disorder characterized by episodes of abnormally increased neuronal discharge resulting in transient episodes of sensory or motor neurological dysfunction, or psychic dysfunction. "First, we tested GRK6 expression in normal brain tissue sample (from epilepsy patients) and various glioma tissue samples (Grade II–IV), all collected freshly at the time of surgery." (PMID 28903336, 2017).
glioma (1 paper, 2017). A benign or malignant brain and spinal cord tumor that arises from glial cells (astrocytes, oligodendrocytes, ependymal cells). "More importantly, there was a increasing tendency of GRK6 expression in higher grade (Grade III–IV) gliomas." (PMID 28903336, 2017). "GRK6 protein and mRNA expression was significantly higher in glioma tissues in comparison with that in the normal brain tissues." (PMID 28903336, 2017). "There results suggest that GRK6 was over-expressed in human glioma tissues, and its upregulation is possible correlated with tumor grade." (PMID 28903336, 2017). "In the current study, we tested the expression and the potential biological functios of GRK6 in human glioma." (PMID 28903336, 2017). "On the other hand, a panel of four GRK6 siRNAs (GRK6 siRNA#1-#4) were transfected to the GRK6-high U251MG glioma cells." (PMID 28903336, 2017). "We show that protein and mRNA expression of GRK6 in human glioma tissues was significantly higher than that in the normal brain tissues." (PMID 28903336, 2017). "The expression and potential biological functions of G protein-coupled receptor kinase 6 (GRK6) in human glioma are tested in this study." (PMID 28903336, 2017). "TMZ's cytotoxicity was only prominent in GRK6-low H4 glioma cells, but was relatively weak in GRK6-high U87MG/U251MG cells." (PMID 28903336, 2017). "We next tested the expression of GRK6 in several human glioma cell lines, including H4, U118, U251MG, U87MG and A172." (PMID 28903336, 2017). "Further immunohistochemistry assay analyzing total 118 human glioma tissues showed that GRK6 over-expression was correlated with glioma pathologic grade and patients’ Karnofsky performance status (KPS) score." (PMID 28903336, 2017). "At the molecular level, in the GRK6-low H4 glioma cells, forced over-expression of GRK6 promoted cell proliferation." (PMID 28903336, 2017). "To further test GRK6 expression in human glioma tissues, we examined 118 paraffin-embedded glioma tissues with different histology grades." (PMID 28903336, 2017). "In current study, we found that expression of GRK6 in human glioma tissues was significantly higher than that in the normal brain tissues." (PMID 28903336, 2017). "First, a Myc-GRK6 construct was transfected to the GRK6-low H4 glioma cells." (PMID 28903336, 2017). "We tested the potential effect of GRK6 on TMZ in glioma cells." (PMID 28903336, 2017). "In the GRK6-low H4 glioma cells, forced-overexpression of GRK6 facilitated cell proliferation." (PMID 28903336, 2017). "On the other hand, siRNA-mediated knockdown of GRK6 inhibited proliferation of U251MG glioma cells." (PMID 28903336, 2017). "Further, the immunohistochemistry assay results examining GRK6 expression in human glioma tissues indicated that GRK6 expression could be correlated with glioma pathological grade and patients’ KPS score." (PMID 28903336, 2017). "Thus, GRK6 over-expression in glioma is important for cell proliferation and temozolomide resistance." (PMID 28903336, 2017). "Temozolomide-induced cytotoxicity was prominent only in GRK6-low H4 glioma cells." (PMID 28903336, 2017). "In summary, our results provide new evidence for the involvement of GRK6 in glioma carcinogenesis, and suggest that RNAi-directed GRK6 silencing may be a potent therapeutic strategy for future glioma treatment." (PMID 28903336, 2017). "One key finding of this study is that GRK6 might be important for glioma cell proliferation." (PMID 28903336, 2017). "Intriguingly, we show that GRK6 could also be an important TMZ resistance factor in glioma cells." (PMID 28903336, 2017). "Thus, over-expressed GRK6 in human glioma cells could positively participate in cancer cell proliferation." (PMID 28903336, 2017). "Thus, GRK6 knockdown could be another way to increase TMZ's sensitivity in glioma cells." (PMID 28903336, 2017).
glioma (continued). "Further analysis showed that GRK6 over-expression (“high”) was correlated with the pathologic grade (P < 0.05) and Karnofsky performance status (KPS) score (P < 0.05) in the glioma patients." (PMID 28903336, 2017). "Furthermore, quantitative results demonstrated that GRK6 expression (protein and mRNA) level was highest in Grade III/IV glioma tissues, but was less higher in grade II glioma tissues." (PMID 28903336, 2017).
lentivirus infection (1 paper, 2016). Virus diseases caused by the Lentivirus genus. "As GFP introduced by lentivirus infection interferes with DCF-DA fluorescence, we measured Trolox-equivalent antioxidant capacity, which was down-regulated by GRK6 knockdown, and was slightly reversed by LA supplementation at 100 μM, and coincides with in vivo observations." (PMID 27882944, 2016).
leukemia (1 paper, 2016). A malignant (clonal) hematologic disorder, involving hematopoietic stem cells and characterized by the presence of primitive or atypical myeloid or lymphoid cells in the bone marrow and the blood. "Given that GRK6 knockout mice are viable, and prominent growth arrest of lymphoid leukemia cell line was observed upon GRK6 knockdown, it might be feasible that GRK6 be used as a potential target for treatment of leukemia." (PMID 27882944, 2016).
lymphopenia (1 paper, 2021). Reduction in the number of lymphocytes. "Interestingly, mice lacking GRK6 exhibit lymphopenia, although GRK6 does not appear to be required for haematopoiesis." (PMID 33466410, 2021).
metastatic tumors (1 paper, 2022). "In HCC, GRK3 was expressed in larger tumors and early stage diseases, whereas GRK6 was prone to expression in smaller, moderate histological grade and metastatic tumors." (PMID 35769816, 2022).
myocardial infarction (1 paper, 2016). Gross necrosis of the myocardium, as a result of interruption of the blood supply to the area, as in coronary thrombosis. "Furthermore, the in vivo experiments also clearly showed that GRK6 was involved in the CSCs migration during myocardial infarction." (PMID 27245949, 2016).
osteoarthritis (1 paper, 2022). A noninflammatory degenerative joint disease occurring chiefly in older persons, characterized by degeneration of the articular cartilage, hypertrophy of bone at the margins and changes in the synovial membrane. "Conversely, GRK6 inhibition could be a potential therapeutic approach to treat osteoarthritis, which is associated with an upregulation of GRK6." (PMID 36555521, 2022). "In osteoarthritis, miR-19b-3p was shown to be downregulated, whereas GRK6 expression levels were elevated." (PMID 36555521, 2022).
thrombosis (1 paper, 2020). "We found that enhanced platelet function in GRK6−/− mice resulted in stable thrombus formation and rapid time to occlusion in in vivo thrombosis models using FeCl3 injury of the carotid artery, indicating that GRK6−/− mice are more susceptible to thrombosis." (PMID 32486261, 2020). "To evaluate the contribution of GRK6 to the platelet function in vivo, we used in-vivo thrombosis models using FeCl3 injury of the carotid artery in WT and GRK6−/− mice." (PMID 32486261, 2020).
cancer (11 papers, 2013 to 2025). A tumor composed of atypical neoplastic, often pleomorphic cells that invade other tissues. "In colorectal carcinoma, GRK6 upregulation was appeared to associate with the metastatic progression and poor outcomes in cancer patients." (PMID 39741338, 2024). "Similarly, overexpression of GRK6 was associated with an increased risk for cancer metastasis and a poorer prognosis in papillary thyroid carcinoma and hepatocellular carcinoma." (PMID 39741338, 2024). "Although GRK6 has attracted increased attention for its role in tumorigenesis, there are few reports that have focused on the regulation of GRK6 in the biological processes of various cancers." (PMID 30984536, 2019). "Both GRK6 and GRK5 have been shown to regulate canonical Wnt signaling, with both genes implicated in increased cellular proliferation, migration, and aggressiveness in a variety of cancer types." (PMID 40424447, 2025). "Antagonism of GRK6, a member of the G-coupled receptor kinase family associated with insulin secretion and T2D susceptibility, and PTK6, an oncogenic kinase studied in the context of cancer, led to the inhibition of T cell activation in the nM to uM range." (PMID 39302339, 2024). "GRK6 decreases the expression of the cancer-promoting genes MMP2 and MMP7." (PMID 33920915, 2021). "Therefore, we speculated that the contrasting function of GRK6 in specific cancers depends on specific receptor proteins or downstream pathways." (PMID 30984536, 2019). "Several other genes residing at the association loci reported include known drug targets with repurposing opportunities, such as GRK6, CD44, SLC38A10, and ADK, with potential implications across multiple different cancers and auto-inflammatory diseases." (PMID 31937769, 2020). "Besides the well-characterised modulators of CDK1, our analysis highlights a novel potential role for MYO3A, GSK3A and GRK6 kinases, whose expression profile is highly correlated with CDK1 itself and its modulators across cancer tissues." (PMID 37898722, 2023). "The description of GRK6 expression and its functional role in cancer is very limited, and until now, has not been reported in MB." (PMID 23497290, 2013).
tumor (9 papers, 2013 to 2024). "Our data showed that the administration of GRK6 inhibitor GRK6-IN-2 at 0.25 mg/kg twice a week dramatically suppressed the lung metastasis and slightly inhibited tumor growth of the MDA-MB231 cell variant." (PMID 39741338, 2024). "Using a murine models of human lung cancer, it has been reported that GRK6 deficiency promotes angiogenesis, tumor progression and metastasis." (PMID 39741338, 2024). "Due to its upregulation in various malign tumour tissues, however, there are several promising efforts to identify specific GRK6 inhibitors in oncological settings." (PMID 36555521, 2022). "With regard to epigenetic modifications of the GRK6 regulation, multiple investigations concerning the methylation status were performed, in particular in the context of malign tumour diseases." (PMID 36555521, 2022). "Our study demonstrated that C/EBPα, a transcription factor of GRK6, inhibited tumor cell migration and invasion in LADC cells by binding to the GRK6 gene promoter." (PMID 30984536, 2019). "The methylation frequencies in the GRK6 gene promoter in LADC tissues were significantly greater than those in the adjacent non‐tumor tissues." (PMID 30984536, 2019). "Compared with adjacent non‐tumor tissues, the expression of GRK6 was downregulated in LADC tissues (P < 0.001)." (PMID 30984536, 2019). "Here, we report that GRK6 mRNA expression levels are downregulated in LADC tissues compared to those in matched adjacent non‐tumor tissues (P < 0.001)." (PMID 30984536, 2019). "Similar to clinical samples, TNBC cell lines HCC38, HCC1806, HCC1937, Hs578T., MDA-MB231, MDA-MB468 and MDA-MB453 exhibited a relatively higher levels of GRK6 as compared to non-tumor mammary cell lines H1845F5 (H184) and MCF10A and ER + cell lines MCF7, T47D and BT-20." (PMID 39741338, 2024). "For example, it was shown that GRK6 mRNA level was upregulated in several tumor cell lines." (PMID 28903336, 2017). "Immunohistochemistry staining (IHS) showed that the expressions of GRK2 and GRK3 were significantly lower in tumor than in adjacent tissues, correlated with disease-free survival and overall survival (OS) in HCC patients, while the GRK6 might mediate a tumor growth signaling." (PMID 35769816, 2022). "A MSP assay was performed to analyze the methylation status of the CpG islands of the GRK6 gene promoter in the LADC tissues and the adjacent non‐tumor tissues of 54 randomly selected cases." (PMID 30984536, 2019). "Robustly, GRK6 knockdown mitigated the lung colony-forming ability of MDA-MB231 cells in comparison with the non-silencing control cells in the tumor-bearing mice." (PMID 39741338, 2024). "Next, we found a decrease trend in GRK6 expression levels in LADC tissues compared with those in non‐tumor tissues using The Cancer Genome Atlas (TCGA) database analysis." (PMID 30984536, 2019). "Furthermore, we compared the binding of C/EBPα with the GRK6 gene promoter between LADC tissues and adjacent non‐tumor tissues by using ChIP‐PCR." (PMID 30984536, 2019). "GRK6 expression is not significantly different between SHH and non-SHH MB, or between histology type, or those alive or deceased in the SHH tumor group." (PMID 23497290, 2013).
infection (1 paper, 2012). The state of being infected such as from the introduction of a foreign agent such as serum, vaccine, antigenic substance or organism. "Quantification of the infected cells after immuno-staining showed a 4 to 5 fold decrease of YFV-17D infection and a 2 to 3 fold decrease of DEN2-NGC infection in the GRK6 −/− MEFs." (PMID 23029581, 2012).
neurological disorders (1 paper, 2013). "In contrast, in neurological disorders, gene therapy has been raised as a potential tool for enhancing GRK6 activity by overexpression." (PMID 23690662, 2013).
GRK6 also shares sentences with these, for which no sentence is quoted: Lewis lung carcinoma (2 papers); Tinnitus (2); acute myeloid leukaemia (1); astrocytoma (1); bacterial infection (1); Chronic colitis (1); colon cancer (1); depression (1); Kaposi's sarcoma (1); lymph node metastasis (1); lymphoid leukemia (1); lymphoma (1); multiple sclerosis (1); prostate carcinoma (1); triple-negative breast carcinoma (1); α-synucleinopathy (1).